FOXM1 (forkhead box M1)
Diseases named in the same sentence as FOXM1 in open-access papers (continued):
Sharing a sentence is not in itself a finding about the gene and the disease.
Sepsis (continued). "Overexpression of FoxM1 in the LECs of these EC-specific HIF-1α knockout mice normalized LEC proliferation and vascular repair, showing that LEC HIF-1α is required for LEC regeneration and vascular repair via FoxM1-mediated EC proliferation after sepsis-induced lung injury." (PMID 35053299, 2022). "Restoration of FoxM1 expression in ECs of these EC-specific Hif1a KO mice normalized endothelial proliferation and vascular repair, demonstrating that pulmonary vascular endothelial HIF-1α is required for lung endothelial regeneration and vascular repair via FoxM1 after sepsis-induced lung injury." (PMID 35563731, 2022). "At enrollment, sepsis was associated with significant increases in the expression of mRNAs related to redox metabolism (myeloperoxidase, 64-fold; PRDX3, 2.6-fold; SOD2, 2.2-fold) and redox-responsive genes (FOXM1, 21-fold; SELS, 16-fold; GLRX2, 3.4-fold)." (PMID 29540208, 2018). "Genes including CCNB1, CCNB2 and TOP2A, as well as transcription factors like FOXM1 might be used as the novel gene therapy targets for sepsis related ARDS." (PMID 27090785, 2016). "To determine whether FoxM1 expression is sufficient to promote endothelial repair following lung injury induced by sepsis, we employed the FoxM1 Tg mice in which expression of human FoxM1 transgene is under the control of the -800-base pair Rosa26 promoter." (PMID 23185540, 2012). "Thus, it is likely that FoxM1 expression in EC is the common critical mediator of endothelial repair following lung vascular injury induced by various sepsis challenges." (PMID 23185540, 2012). "Especially, it is unknown if FoxM1 is critical for endothelial repair following polymicrobial sepsis induced by cecal ligation and puncture (CLP), a well-recognized clinically relevant rodent model of sepsis." (PMID 23185540, 2012). "However, it remains unclear whether FoxM1 expression is sufficient to promote endothelial repair in experimental models of sepsis." (PMID 23185540, 2012). "We also found that CXCL12 induced FoxM1 expression in lung ECs via p110γ PI3K→ FoxO1 signaling and mediating endothelial regeneration in sepsis-induced inflammatory lung injury." (PMID 33804745, 2021). "Another study indicated that the upregulation of FOXM1 and its downstream targets CCNB1, CCNB2 and TOP2A is involved in sepsis-related ARDS." (PMID 30992007, 2019). "We showed that transgenic expression of FoxM1 resulted in rapid recovery of vascular integrity and resolution of lung inflammation following CLP-induced polymicrobial sepsis." (PMID 23185540, 2012). "Upstream of FoxM1, the transcription factor HIF-1α (hypoxia-inducible factor 1-alpha) plays a pivotal role in ECs-mediated vascular repair and inflammation resolution, making it another attractive therapeutic target for sepsis-induced ARDS." (PMID 40476000, 2025). "The final aim was to determine whether Rabeprazole improves vascular repair and the resolution of sepsis-induced inflammatory lung injury via HIF-1α and FoxM1." (PMID 35563731, 2022). "Furthermore, animal models of lung injury have shown that FOXM1 is essential in regulating neutrophil response and secretion of MPO and cathepsin G, both of which were enriched in neonates that did not survive sepsis." (PMID 40655143, 2025).
squamous cell carcinoma (11 papers, 2009 to 2023). A carcinoma arising from squamous epithelial cells. "The quantitative Malignancy Index Diagnostic System (qMIDS) was the first FOXM1 oncogene-based diagnostic test developed for quantifying squamous cell carcinoma aggressiveness." (PMID 27409343, 2016). "In 2013, we have developed a FOXM1-oncogene associated multi-biomarker ‘quantitative Malignancy Index Diagnostic System’ (qMIDS) for quantifying the aggressiveness of squamous cell carcinoma (SCC)." (PMID 27409343, 2016). "FOXM1 overexpression leads to DNA methylation changes in oral keratinocytes, including a global hypomethylation phenotype similar to that present in a squamous cell carcinoma cell line." (PMID 32213861, 2020). "FOXM1 protein levels are increased in adenocarcinoma, squamous cell carcinoma, adenosquamous carcinoma, large cell neuroendocrine carcinoma (LCNEC) and small cell neuroendocrine carcinoma (SCLC) compared with those in corresponding normal lung tissues." (PMID 30992007, 2019). "FOXM1 depletion sensitizes both normal keratinocytes and squamous carcinoma cells to apoptosis and ROS-induced apoptosis." (PMID 27385468, 2016). "FOXM1 depletion sensitizes normal keratinocytes and head and neck squamous carcinoma cells to apoptosis." (PMID 27385468, 2016). "More recently, FOXM1 was shown to be overexpressed and of potential prognostic significance in oesophageal adenocarcinomas and squamous carcinomas." (PMID 26576650, 2015). "Together, these data identify FOXM1 as a key regulator of ROS in normal dividing epithelial cells and suggest that squamous carcinoma cells may also use FOXM1 to control oxidative stress to escape premature senescence and apoptosis." (PMID 27385468, 2016). "Finally, our results also indicated that squamous carcinoma cells uses FOXM1 to control oxidative stress to escape premature senescence and apoptosis." (PMID 27385468, 2016). "We observed increased FOXM1 and SHH RNA expression in NSCLC cells and CSC‐treated Beas‐2B cells, even though the protein expression of both were predominant in H1703 (squamous cell carcinoma) and HCC827 (adenocarcinoma) cell lines, respectively." (PMID 36621828, 2023). "In the same fashion, the FOXM1 target gene PLK1 has also been shown to be overexpressed in a wide range of tumours, including oesophageal adeno- and squamous carcinomas." (PMID 26576650, 2015).
esophageal adenocarcinoma (10 papers, 2009 to 2025). A malignant tumor with glandular differentiation arising predominantly from Barrett mucosa in the lower third of the esophagus. "As for specific effects of FOXM1 on immune cell populations, one study in esophageal adenocarcinoma suggested FOXM1 inhibits CD8+ T cell chemotaxis, tumor infiltration, and tumor cell killing, in part through regulation of Th1 chemokine expression." (PMID 39347707, 2024). "Recently, a positive correlation between UBE2C and FOXM1 gene expression in esophageal adenocarcinoma (EAC) samples and in vitro EAC-derived cells was reported." (PMID 29596365, 2018). "In esophageal adenocarcinoma, changes in the expression of network genes regulated by FOXM1 have been useful in predicting prognosis." (PMID 29682174, 2018). "Analyses of malignant cancer tissues showed that FOXM1 was significantly upregulated in HNSCC (3.1-fold), oesophagus adenocarcinoma (3-fold) and lung malignant mesothelioma (2.4-fold)." (PMID 19287496, 2009).
lung diseases (10 papers, 2019 to 2024). "In kidney disease, lung disease, heart disease, and brain disease, FOXM1 regulation reduces inflammatory responses and apoptosis, promoting tissue repair and regeneration." (PMID 37238726, 2023). "For the first time, this review summarizes the mechanistic relationship between FOXM1 dysregulation and pulmonary diseases, the benefits of targeting abnormal FOXM1 expression, and the questions that remain to be addressed in the future." (PMID 30992007, 2019). "Intriguingly, emerging evidence indicates that FOXM1 plays a key role in lung diseases." (PMID 35279083, 2022). "After 20 years of research, FOXM1 was shown to be closely related to pulmonary diseases." (PMID 30992007, 2019). "Several studies have shown that FOXM1 is involved in pulmonary diseases." (PMID 30992007, 2019). "On a separate note, forkhead box M1 (FOXM1), belonging to the FOX family of transcription factors, is a crucial player in pulmonary diseases." (PMID 36964598, 2023).
metastatic melanoma (10 papers, 2015 to 2023). A melanoma that has spread from its primary site to another anatomic site. "The forkhead box protein M1 (FOXM1) transcription factor has been reported to express at higher levels in metastatic melanoma, and is closely implicated in the regulation of many biological processes, such as cell proliferation, apoptosis and cell cycle." (PMID 35138218, 2022). "An immunohistochemical analysis of the FOXM1 expression in 43 primary cutaneous melanoma, 12 metastatic melanoma and 20 melanocytic nevus tissue specimens was performed." (PMID 26640950, 2015). "In this study, we found that the metastatic melanoma samples exhibited significantly higher mRNA expression levels of FOXM1 (p = 0.004)." (PMID 26640950, 2015). "Among the top 5 candidate genes (UBE2C, ASF1B, FOXM1, HJURP, and KIF18B), UBE2C was the most frequently associated with poor prognosis in publicly available clinical datasets from diverse cancer types, including metastatic melanoma." (PMID 37215954, 2023). "Additionally, a FOXM1 inhibitor, a thiazole antibiotic, siomycin A, was reported to induce apoptosis in metastatic melanoma cell lines that correlated with the downregulation of FoxM1." (PMID 26640950, 2015). "FOXM1 inhibition might be a promising treatment strategy for metastatic melanoma." (PMID 36467505, 2022). "Notably, the top 20 genes from topological analysis algorithms included four hub genes: CDK1, FOXM1, KIF11, and RFC4, which may involve in the development of metastatic melanoma." (PMID 35906389, 2022).
oral cancer (10 papers, 2009 to 2024). "They demonstrated that the overexpression of FOXM1 protein induced by cisplatin causes resistance to paclitaxel, which can potentially attenuate the effectiveness of the combination with the two chemotherapeutic agents for oral cancer." (PMID 37189730, 2023). "Previous studies found that FOXM1 dysregulation can cause abnormal cell proliferation, thereby leading to carcinogenesis; its overexpression has been observed in many types of cancer including lung, liver, breast, brain, and oral cancers." (PMID 31877715, 2019). "Our finding that FOXM1 is upregulated early during oral cancer progression renders FOXM1 an attractive diagnostic biomarker for early cancer detection and its candidate mechanistic targets, CEP55 and HELLS, as indicators of malignant conversion and progression." (PMID 19287496, 2009). "Our results further suggest that the overexpression of FOXM1 protein by cisplatin makes it difficult to overcome drug resistance to cisplatin and causes resistance to paclitaxel, which can potentially attenuate the effectiveness of combination chemotherapeutics on oral cancer." (PMID 33255409, 2020). "To further examine the role of FOXO3a and FOXM1 in vivo, we first used an orthotopic nude mouse model of oral cancer, in which UM-SCC-1 stable cell lines were injected into the tongues of nude mice." (PMID 29269868, 2018). "High FOXM1 expression was reported in many cancers including oral cancer." (PMID 35378133, 2022). "Additionally, high FOXM1 expression is involved in the migration and invasion of oral cancer cells, implying that FOXM1 plays an important role in regulating the aggressive behavior of cancer cells." (PMID 35313071, 2022).
renal carcinoma (10 papers, 2014 to 2024). A carcinoma arising from the epithelium of the renal parenchyma or the renal pelvis. "Cell cycle arrest and senescence is reported to be induced in MYBL2 or FOXM1 deficient cells, while overexpression of FOXM1b contributes to the pathogenesis of many cancers i.e., colorectal, nasopharyngeal and renal cancer." (PMID 35409296, 2022). "It has been recently observed that MIR320A suppresses tumor cell proliferation and invasion of renal cancer cells by targeting forkhead box protein M1 (FoxM1)." (PMID 33550766, 2021). "Several studies have confirmed the vital role of FOXM1, which may serve as an essential prognostic biomarker and therapeutic target for renal cancer." (PMID 36585925, 2022). "OTUB1 mediates the deubiquitination of FOXM1 to promote renal cancer tumor progression." (PMID 36339263, 2022). "The results showed that EIF4EBP1, FOXM1, PLG, and VWF were highly expressed in renal carcinoma compared with normal renal tissue, and ADAM8, CGN, G6PC, ITIH4, and MMP3 were low in expression in renal carcinoma compared with normal renal tissue." (PMID 33968297, 2021).
thyroid cancer (10 papers, 2016 to 2025). "This analysis revealed that seven of the novel identified variants were located in genes previously associated with thyroid cancer: MSH6, FOXM1, EPCAM, HOOK3, BMP1, TG and NTRK1." (PMID 37175550, 2023). "The information on possible FOXM1 and Bcl-xL connections is very scarce and is limited to two reports describing positive correlation between these proteins in thyroid cancer and pancreatic β-cells." (PMID 34381718, 2021). "For instances, LINC01410 silencing retards cell proliferation and facilitates apoptosis via regulating miR‐3619‐5p/FOXM1 axis in thyroid carcinoma." (PMID 32886453, 2020). "Induction of apoptosis following CDK4/6 inhibition in thyroid cancer cells involved a modulation of FOXM1, cyclin A1 and myc." (PMID 30349650, 2018). "However, thanks to master regulator analysis, we at least observed that FOXM1 transcriptional targets are upregulated in thyroid cancer when compared to normal thyroid tissue." (PMID 39858603, 2025). "Our results strikingly show that FOXM1 is upregulated in all the 15 tumor types, with a significant (padj < 0.01) adjusted p-value (derived from the DESeq2 negative binomial test) in 14 out of 15, the only exception being thyroid cancer, with padj = 0.3422." (PMID 39858603, 2025). "FOXM1 expression increased in 29 groups of analyses and decreased only in thyroid carcinoma." (PMID 38608123, 2024). "Several transcription factors including E2F7, FOXM1, NFYB, and CREB3L1 were significantly associated with the OS of thyroid cancer patients and may be the main regulators of ATC progression." (PMID 36192735, 2022). "GRB7 also modulated the proliferation, cell cycle, migration and invasion of bladder and thyroid cancer via the AKT pathway and GRB7/ERK/FOXM1 signaling cascade." (PMID 39204147, 2024).
fibrosis (9 papers, 2011 to 2026). the formation of excess fibrous connective tissue in an organ or tissue in a reparative or reactive process. "For instance, in cardiomyocytes Foxm1 loss leads to cardiac fibrosis, and in Clara cells, its loss during development leads to peribronchial fibrosis." (PMID 38916959, 2024). "Foxm1 deletion in developing cardiomyocytes caused embryonic lethality, decreased cardiomyocyte proliferation, diminished vascular density in the myocardium and induced cardiac fibrosis in the early postnatal period." (PMID 21779394, 2011). "Here, we demonstrated that transcriptional factor FoxM1 was significantly increased in obstructed kidneys and patients' kidneys with fibrosis." (PMID 33434361, 2021). "Targeting FOXM1 with peptide-based PROTACs may provide a promising therapeutic strategy to attenuate liver fibrosis and suppress HCC development." (PMID 42094592, 2026). "Fibroblast-specific deletion of Foxm1 inhibits fibroblast proliferation, MYF differentiation and therefore protects mice from bleomycin-induced fibrosis." (PMID 34497269, 2021).
laryngeal squamous cell carcinoma (9 papers, 2020 to 2025). A squamous cell carcinoma that arises from the larynx. "Furthermore, NAT10-mediated ac4C modification of forkhead box M1 (FOXM1) in the 3’-untranslated region promoted the malignant processes of laryngeal squamous cell carcinoma (LSCC) cells." (PMID 41316475, 2025). "Similarly, miR-370 functions as a tumor suppressor in laryngeal squamous cell carcinoma (LSCC) by targeting FoxM1." (PMID 35356749, 2022).
medulloblastoma (9 papers, 2018 to 2025). A malignant, invasive embryonal neoplasm arising from the cerebellum. "In tissue samples obtained from medulloblastoma patients, the significant upregulation of FOXM1 was associated with a loss of its putative regulating microRNA, miR-4521." (PMID 31541075, 2019). "An additional candidate, FOXM1, was selected because FOXM1 has been reported to be a target of miR-4521 in medulloblastoma." (PMID 33407516, 2021). "To understand the underlying mechanism, we investigated the effect of miR-4521 on the expression of the transcription factor FOXM1 in medulloblastoma cell lines." (PMID 31541075, 2019). "FOXM1, a proliferation-specific oncogenic transcription factor, is deregulated in various solid tumors, including medulloblastoma, and triggers cellular proliferation, migration and genomic instability." (PMID 31541075, 2019). "miR-4521 has been reported to target FOXM1 in medulloblastoma." (PMID 33407516, 2021). "Additionally, in the medulloblastoma, low levels of miR-4521 leads to an up-regulation of the transcription factor forkhead box M1 (FOXM1)." (PMID 34944941, 2021). "FOXM1 is highly expressed in all medulloblastoma molecular subgroups." (PMID 33101383, 2020). "In conclusion, a restoration of miRNA-4521 may selectively suppress the pathophysiological effect of aberrant FOXM1 expression and serve as a targeted approach for medulloblastoma therapy." (PMID 31541075, 2019). "Further, downstream targets of FOXM1 such as PLK1 and cyclin B1 were significantly reduced thus affecting the cell cycle progression in medulloblastoma cell lines." (PMID 31541075, 2019).
oral squamous cell carcinoma (9 papers, 2013 to 2023). "Moreover, overexpression of FOXM1 was previously reported to contribute to the elevated migratory and invasive abilities in oral cavity squamous cell carcinoma, indicating that FOXM1 was associated with an aggressive behavior of tumor cells in vitro." (PMID 24004449, 2013). "Furthermore, CEP55 drives the migration and invasion of oral cavity squamous cell carcinoma by increasing FOXM1 and MMP-2 activity." (PMID 37484531, 2023). "In addition, expression of CEP55 was correlated with aggressiveness of oral cavity squamous cell carcinoma by stimulating cell migration and invasion through increased FOXM1 and MMP-2 activity." (PMID 26615423, 2016).